CD4 (CD4 molecule)
Diseases named in the same sentence as CD4 in open-access papers (continued):
Sharing a sentence is not in itself a finding about the gene and the disease.
malaria (continued). "In some cases, this is accompanied by increases in FoxP3+ regulatory CD4+ T cells, though Tregs decrease after multiple incidences of malaria." (PMID 36131528, 2022). "During the erythrocytic stage of malaria, CD4+ T cells play a crucial role in regulating the immune response." (PMID 36094170, 2022). "In endemic settings, the frequency of IL-10-producing CD4+ T cells correlated with the number of malaria exposures." (PMID 36389662, 2022). "Despite being key drivers of protective antibodies against malaria, little is known regarding the host and parasite factors that influence CD4 T-follicular helper cell and antibody development." (PMID 35851033, 2022). "In Plasmodium, CD4+ T cells displayed a central role against parasitized erythrocytes after being activated by antigen-presenting cells during blood-stage malaria." (PMID 35812841, 2022). "It has been postulated that HIV increases malaria incidence in adults based on CD4+ cell count categories." (PMID 36104731, 2022). "More recently, the P2 universal CD4+ T cell epitope (aa 830–844) of tetanus toxoid (TT-P2), has been demonstrated to enhance the immunogenicity of a peptide vaccine for malaria and an epitope-based vaccine for rotavirus in mice or guinea pigs." (PMID 35062983, 2022). "Cytokine producing CD4+ T cells have been shown to play an important role in protection against P. falciparum infection following immunization with the malaria vaccine RTS, S." (PMID 35715803, 2022). "Malaria-specific IFNγ+CD4+ T cells have been previously identified as a correlate of protection in the context of vaccination and natural infection." (PMID 35922467, 2022). "Particularly, TNFα-secreting CD4+ T cells in response to malaria antigen stimulation, at baseline and after immunization, were associated with protection." (PMID 35062785, 2022). "As a result, World Health Organization (WHO) recommends cotrimoxazole preventive therapy (CPT) lifelong for PLHIV in resource-limited settings where malaria and, or severe bacterial infections are highly prevalent, irrespectively of their CD4 count." (PMID 35231047, 2022). "A subunit malaria vaccine confers protection against sporozoite challenge by increasing the production of IL-2-secreting CD4+T cells." (PMID 36504817, 2022). "It has also been shown that elevated levels of CD161+CD4+ T cells and malaria-specific IFN-γ-production predicted protection against CHMI." (PMID 35715803, 2022). "In this study, we have found that IFNγ-producing CD4+ T cells and DN γδ T cells co-producing IFNγ and TNF are associated with parasite control among lifelong malaria-exposed Africans." (PMID 35922467, 2022). "This analysis predicted CD4+ T cells as the main sources of asymptomatic malaria transcriptional profiles." (PMID 35475529, 2022). "Blood-stage malaria is characterized by overwhelming activation of CD4+ as well as CD8+ T cells, both of which secrete pro-inflammatory cytokines." (PMID 35874786, 2022). "Recent information also indicates that malaria is associated with the availability of ART and CD4+ cell count numbers in adults." (PMID 36104731, 2022). "Antibody induction during infection, including malaria, is driven by T-follicular helper CD4 T cells." (PMID 35851033, 2022). "The impact of HIV on the severity of malaria appears to be restricted to patients with CD4 + T cell counts < 350 cells/μL." (PMID 33407474, 2021). "Our data indicate that the D/Ad-PfCA malaria vaccine mainly alter the CD4+ T cell component in circulation, inducing persistent changes over 6 months post-last exposure." (PMID 33732548, 2021). "Type I IFN signalling has been shown to be an important driver of Tr1 cell responses in human malaria infection and parasite-specific Tr1 cells dominate CD4+ T cell responses in malaria." (PMID 36845571, 2021).
malaria (continued). "CD4+ T cells play critical roles in the immunoregulatory pathways established during malaria by priming for phagocytosis mediated killing of parasitized RBCs, and by helping B cell differentiation to produce functional anti-Plasmodium antibodies." (PMID 34414129, 2021). "Previous studies have suggested that the malaria parasite can inhibit the activation of parasite-specific CD4+ T-cell responses by inducing the apoptosis of DCs, downregulating co-stimulatory molecules, and/or suppressing antigen presentation by DCs." (PMID 34987497, 2021). "Due to the central importance of Tfh cells in antibody development, targeting this CD4+ T cell subset has been proposed as an avenue to improve vaccine efficacy, including in malaria." (PMID 36845571, 2021). "The role of CD4 + T cells in protective immunity against malaria parasite liver stages is achieved when they directly inhibit the development of the parasites and indirectly contribute towards the function of CD8 + T cells." (PMID 34666102, 2021). "IL-4-secreting CD4+ T cells have been shown to be critical for the induction of CD8+ T-cell response to liver-stage malaria." (PMID 34696180, 2021). "Inflammatory CD4+ T cells offer protection against malaria by producing IFNγ and TNFα such that P. falciparum infection or its replication is inhibited, thus preventing severe malaria." (PMID 34414129, 2021). "With regard to malaria an effective vaccine requires long-lasting primary and memory antigen-specific CD4+ T cell, B cell, and CTL responses." (PMID 34696180, 2021). "Subsequently, it was shown that P2X7, a receptor for extracellular ATP, was indeed activated in CD4+ T cells during malaria following the rupture of infected erythrocytes." (PMID 36845571, 2021). "Depletion of CD25+ Treg cells significantly reversed the inhibition of CD4+ T-cell proliferation and IL-2 production, indicating that this cell population contributes to the suppression of T-cell function during malaria." (PMID 34414129, 2021). "EBNA1-specific IFN-γ-producing CD4+ T cell response rates were lowest in eBL (40%) compared to children with high malaria (84%) and low malaria (66%) exposures (p < 0.0001 and p = 0.0004, respectively)." (PMID 34771539, 2021). "For example, changes in red blood cell counts in investigations of malaria or changes in CD4+ counts in immunodeficiency virus investigations." (PMID 33635869, 2021). "In humans, the malaria parasite induces DC apoptosis and thereby inhibits parasite-specific CD4+ T cell responses to facilitate its survival, along with downregulating costimulatory molecules on DCs." (PMID 33995336, 2021). "It has been suggested that HIV-1 infections worsen P. falciparum presentations by depleting the CD4 T-cell compartment, essential for driving malaria-specific antibody responses and for clearance of malaria infected red blood cells." (PMID 33499880, 2021). "In this study, 42.1% of patients with malaria infection had CD4 + T cell counts of less than 200 cells/μL, and one of them had severe malaria." (PMID 33407474, 2021). "A previous study suggested that the incidence of clinical malaria episodes was reported to be higher in patients with a CD4 cell count of < 200 cells/μL compared with those with a CD4 cell count of > 500 cells/μL50." (PMID 34404814, 2021). "A recent review of the role of IFN-γ in malaria suggests that type I IFN signaling limits CD4+ T helper cell activity during the blood infection stage." (PMID 34790829, 2021). "Although CpG has been reported to be able to significantly enhance the malaria parasite-specific CD4+ T responses and reduce the vaccine dose from 108 to 103, the use of CpG as an adjuvant in humans has not been approved." (PMID 33995336, 2021). "The advent of computational vaccinology and increasing availability of tools has resulted in an influx of publications utilizing in silico CD4 T cell epitope analysis to rationally design vaccines, including those targeting malaria." (PMID 34168657, 2021).
malaria (continued). "These two observations suggest that human immune response is controlled by distinct CD4 + T cell subsets that correspond to Th1 and Th2 cells and that both helper and effector functions of CD4 + T cells contribute to malaria immunity." (PMID 34666102, 2021). "In malaria, CD4+ T cells have an immunosuppressive function, inducing a Th1-type immune response that consequently inhibits B cell activity." (PMID 34790829, 2021). "Children having the lower CD4 count (240–400 CD4 cells/mm3) were more likely to be positve for malaria (20% compared to 10.8%; X2 = 0.71, p = 0.4); for HIV (40% compared to 0%; X2 = 31.08; p<0.001) and for dengue(20% compared to 5.3%; X2 = 2.96, p = 0.085)." (PMID 33861747, 2021). "Our previous data also indicated that the C5a/C5aR signaling pathway in dendritic cells (DCs) was activated during immunization and is essential for the optimal induction of the malaria parasite-specific CD4+ T cell response." (PMID 33995336, 2021). "Several reports indicate that most of the malaria vaccines work mainly by inducing protective serum antibodies and to some extent CD4+ T cells which is often a sufficient component of vaccine efficacy." (PMID 34269931, 2021). "To date, there are only limited studies of the role of gut microbiota in CD4+ T cell responses in malaria." (PMID 36845571, 2021). "Conversely, more recently, viral vectors encoding PfCelTOS did not yield protective immunity in either BALB/c or CD1 mice using rodent malaria transgenic parasites, even in the presence of antibodies and PfCelTOS-specific CD4+ and CD8+ T cells." (PMID 33572803, 2021). "In contrast, Kisumu children had similar frequencies of cytokine responders to the EBV and malaria antigens used in our assay, while children diagnosed with eBL had significantly more CD4+ T cell IL-17A responders to EBNA1 compared to PfSEA-1A (p = 0.0004)." (PMID 34771539, 2021). "Experiments in rodent malaria models have shown that a CD4+ Th1 response is needed to control the first phase of infection by limiting the parasitemia." (PMID 34696180, 2021). "The study showed an inverse relationship between the CD4 count and the malaria parasite placenta density." (PMID 32103782, 2020). "Here, using bulk TCRβ repertoire sequencing we examine the dynamics and clonal structure of the splenic CD4+ T-cell repertoires generated during infection with the well-established mouse malaria model Plasmodium chabaudi (AS)." (PMID 33329568, 2020). "As such, we examined PD1hi expression on CD4 T cells, which are known to mediate survival from malaria." (PMID 32733457, 2020). "Intriguingly, we found that LD01 treatment of mice in the lethal malaria model significantly reduced the numbers of splenic FOXP3+Tbet+CD4+ Tregs compared to anti-PD1 mAb-treated mice." (PMID 32733457, 2020). "During blood-stage malaria, CD4+ T cell-intrinsic IFN-I signaling induces T-bet and Blimp-1 expression, thereby promoting IL-10+ Tr1 responses in mice as well as in humans." (PMID 32265335, 2020). "Our findings revealed that the infusion of MSCs from malaria-infected animals was able to rescue the proliferation of CD4+ T cells." (PMID 33298881, 2020). "A recent study demonstrated that malaria-specific CD4+ T cells produce IL-27 and regulate protective immunity during malaria parasite infection." (PMID 33584666, 2020). "In experimental malaria, IL-27 has been suggested to regulate protective immunity partly through IL-27 producing CD4+ T cells." (PMID 31964363, 2020). "The protective role of CD4+ T cells during murine malaria is largely assumed to derive from their robust production of IFN-γ, as IFN-γ is also critical for controlling parasitemia." (PMID 32043415, 2020). "Accordingly, we observed a significant increase of LAG-3 and TIM-3 on CD8+ and CD4+ T cells in malaria patients when compared to healthy donors." (PMID 32983106, 2020).
malaria (continued). "People with HIV-malaria co-infection were reported to have low immunity and reduces CD4 count, and the risk of death in PLHA coinfected with malaria is also reported high due to low anti-retroviral therapy (ART) treatment adherence." (PMID 33292761, 2020). "CD4+ T cells are well established as both critical mediators of anti-parasitic defenses during malaria and as targets for negative regulation by TGF-β." (PMID 32043415, 2020). "CD4+ T cells from 18 patients with P. falciparum or P. knowlesi malaria were assessed by flow cytometry and sorted into populations of CD4hiCD38hi or CD4norm T cells." (PMID 33282291, 2020). "There was an inverse relationship between CD4 count at booking and 36 weeks with the malaria placenta density with P-value of < 0.01 and 0.01, respectively." (PMID 32103782, 2020). "In the context of experimental rodent malaria, IL‐27 (acting via the IL‐27 receptor) was shown to induce the generation of IL‐10‐expressing CD4+ T cells that were critical to limit immunopathology." (PMID 33282291, 2020). "In a phase 3 clinical trial in Africa, RTS,S elicited modest protection against clinical malaria that correlated with CSP antibody and CD4+ T cell responses, suggesting that antibodies to sporozoites can mediate protection against malaria." (PMID 32407410, 2020). "Flow cytometric analysis of PBMCs from patients with either P. falciparum or P. knowlesi malaria revealed a pronounced population of CD4+ T cells co‐expressing very high levels of CD4 and CD38 we have termed CD4hiCD38hi T cells." (PMID 33282291, 2020). "Overall, these data suggest a model where Tregs act in a discrete temporal window during blood-stage malaria, in part to limit CD4 TH1 responses." (PMID 32043415, 2020). "We choseCD4+ cells due to their key roles in the immune system, being forexample the reservoir of HIV but also an interesting target for immune therapiesapproaching exhaustion of CD4+ cells due to malaria." (PMID 32788917, 2020). "CD4+ TH1 cells expand in numbers during malaria in mice and humans, and help control parasitemia during blood-stage malaria." (PMID 32043415, 2020). "CD4+ T cells orchestrate protective immunity to blood-stage malaria by activating macrophages to kill the parasite and helping B cells produce Ab." (PMID 32817333, 2020). "In animal models of malaria, a Plasmodium infection in previously unexposed individuals initially produces a massive expansion of CD4+ T-cells in the spleen, a major site of the developing immune response." (PMID 33329568, 2020). "In most cases of acute falciparum malaria or knowlesi malaria, we observed a distinctive and unexpected population of CD4+ T cells that co‐expressed high levels of CD38 and CD4, which we have termed CD4hiCD38hi cells." (PMID 33282291, 2020). "This increase of PD1 on T cells in malaria was significant across all memory subsets of CD4+ T cells and on naïve and EMRA CD8+ T cells." (PMID 32983106, 2020). "We showed previously, in a mouse malaria model, that DCs are a primary target for mediating the suppressive activity of type I IFNs on CD4+ T cell responses." (PMID 32101732, 2020). "For people living in malaria endemic regions, a threshold CD4 count of < 350 cells/mm3 was indicative of cotrimoxazole preventive therapy for adults and adolescents to prevent malaria and other bacterial infections." (PMID 33883764, 2020). "Our group recently used the P. yoelli 17XNL model of infection to show that CD4+ Foxp3+ Tregs expand during a specific temporal window of blood-stage malaria." (PMID 32043415, 2020). "IFNλ signals appears to influence the CD4+ T cell response during blood-stage malaria in an indirect fashion." (PMID 32407154, 2020). "CD4 T cells in adults from malaria-endemic areas also express cytokines of multiple lineages including IFN-γ, IL-10, and IL-21, even in cells with a Tfh-like phenotype." (PMID 32634740, 2020).
malaria (continued). "We were curious as to why no analogue of the CD4hiCD38hi cell population has been yet reported in mice, given the very large number of immunological studies performed utilising rodent malaria models including those focused on the role of CD4+ T cells." (PMID 33282291, 2020). "While it is clear that CD4 T cells are involved in protective immunity against malaria, its use as a potential correlate of protection needs further validation." (PMID 31231377, 2019). "Type I IFNs suppress CD4+ T cell-dependent parasite control during experimental blood-stage malaria by modulating the function of CD8α− cDC following P. berghei ANKA infection, rather than acting directly on CD4+ T cells." (PMID 30809232, 2019). "Patient HH-21 was infected with P. vivax and not with P. falciparum but the EXP1-specific cultures nevertheless elicited a CD4+ T cell response against EXP1-P15 indicating that immunity against malaria can indeed be cross-species specific." (PMID 32038611, 2019). "Of note, the induction and role of GrzB producing CD4+ T cells in malaria has already been analyzed and discussed before." (PMID 31921176, 2019). "All the participants enrolled into the study had their blood samples assessed for malaria parasite densities before commencement of antimalarial therapy and the results correlated with their CD4 T-cells levels obtained from their respective files." (PMID 31354844, 2019). "Our previous studies of protective immunity and pathology against blood stage malaria parasites have shown that not only CD4+ T cells, but also CD8+ T cells and macrophages, are important for host defense against blood stage malaria infection." (PMID 31608052, 2019). "The WHO criteria for co-trimoxazole prophylaxis among PLHIV are CD4 count ≤350 cells/mm3 or clinical stage 3 or 4, or lifelong co-trimoxazole for any CD4 count in settings with a high prevalence of malaria or bacterial infections." (PMID 30876400, 2019). "Levels of CD4+CD57+ T cells were significantly higher in children with symptomatic malaria compared to asymptomatic (p = 0.0006) and healthy controls (p = 0.0041)." (PMID 31316497, 2019). "A partial correlation matrix with covariates between the cellular markers measured on CD4+ T cells for the symptomatic malaria population." (PMID 31316497, 2019). "Blood samples were tested for malaria blood smear, rapid malaria diagnostic test (RDT), complete blood count, haematological film analysis, HIV serology, and CD4+ and CD8+ cell counts." (PMID 31428162, 2019). "This agrees with the known profile of AS01TM, which has been shown to robustly induce CD4 T cells to malaria and varicella-zoster antigens in preclinical and clinical studies." (PMID 31816920, 2019). "The spleen is the major site of immune responses to blood-stage malaria and is important for the accumulation of innate immune cells including dendritic cells and NK cells as well as CD4+ T cells and B cells involved in adaptive immunity." (PMID 30915078, 2019). "Levels of CD28-CD57+CD4+ T cells were also increased in children with symptomatic malaria compared to children with asymptomatic infections (p = 0.0002) and healthy controls (p = 0.0064)." (PMID 31316497, 2019). "This study aimed to comprehensively define the breadth and specificity of the Plasmodium falciparum (P. falciparum)-specific CD4+ T cell response directed against the exported protein 1 (EXP1) in a cohort of patients diagnosed with acute malaria." (PMID 32038611, 2019). "It is therefore crucial to investigate the immune effects of malaria and TB coinfection on the CD4 and CD8 cells which have a key role in TB immune responses alongside macrophages and other innate immune mechanisms." (PMID 31428162, 2019). "To understand the relationship between T-bet and CXCR3 expression during blood-stage malaria, we determined if these markers are co-expressed by CD4+ T cell populations in the spleen." (PMID 30915078, 2019).